MITF (melanocyte inducing transcription factor)
Diseases named in the same sentence as MITF in open-access papers (continued):
Sharing a sentence is not in itself a finding about the gene and the disease.
melanoma (continued). "MITF levels are higher in melanocytes than melanoma cells, inversely correlated with AXL and FSCN1, but FRA1 modulation did not alter MITF levels, consistent with RNA-seq and Cut&Run data showing no direct FRA1 regulation of MITF." (PMID 41286309, 2025). "Metastatic melanoma is characteristically negative for cytokeratins and squamous markers but shows strong positivity for melanocytic antigens, including S100, SOX10, Melan-A, HMB-45, and MITF." (PMID 41234990, 2025). "Apparently, although MITF serves as a positive regulator of Ddit4l, elevated MITF activity did not enable substantial REDD2 expression in R722W melanocytes, indicating that additional factors contribute to REDD2 expression in R722W melanoma cells." (PMID 40918647, 2025). "An example of this is MITF, which is not always regulated by PAX3 in melanoma." (PMID 40428399, 2025). "In our cohort, while tumors that have MiTF pathway activation without TFE3 rearrangement (i.e., granular cell tumor and melanoma) demonstrated TRIM63 RNA hybridization, they generally did so at a lower level than that of ASPS, with lower average H-scores (p < 0.05)." (PMID 38393424, 2024). "Strikingly, we find that p300 KAT activity is essential for SOX10 protein stability and that inhibition of p300 KAT with the small-molecule inhibitor A-485 inhibits the expression of SOX10 target genes and SOX10-dependent melanoma growth in SOX10+ melanoma cell lines, regardless of the MITF status." (PMID 38994683, 2024). "First, we could confirm the results from the digital spatial profiling analysis showing a decreased expression of MITF in PD1res melanomas, however not reaching statistical significance when compared to CTLA4res or ICB naïve melanomas." (PMID 38594286, 2024). "We co-expressed Flag-tagged versions of the non-DNA binding mutant proteins MITF-Wh, MITF-mi, and MITF-ew together with the MITF-WT-GFP, MITF-sp-GFP, or MITF-sl-GFP proteins in A375P melanoma cells which express little endogenous MITF followed by co-immunoprecipitation (co-IP) using FLAG-antibodies." (PMID 39169200, 2024). "Thus, melanoma cells can exhibit different phenotypic states based on the heterogeneous expression of MITF in the same tumor bed, regardless of whether the cell lines have a mainly invasive (MITF negative) or proliferative (MITF positive) phenotype in vitro (also see Section 5, below)." (PMID 36675114, 2023). "In both proliferative phenotype melanoma cell lines, knockdown of SMAD4, TAZ, and β-catenin, but not of YAP, significantly counteracted the TGFβ-induced down-regulation of the expression of the melanocyte markers MITF and MLANA." (PMID 34819356, 2022). "While SNAI2 was shown to be positively correlated with MITF, the expression of CDH1 did not correlate with the expression of SNAI2 in the TCGA melanoma tumors which is consistent with the published findings in melanoma and melanocyte samples, despite CDH1 being a canonical target of SNAI2." (PMID 33438577, 2021). "Unlike irradiated parental B16/F10 melanoma cells which form lung tumors in nude mice but not in immunocompetent mice owing to T-cell-mediated immune rejection, the ADAM10-KO cells behave like MITF-KO cells in that they fail to form tumors in nude mice." (PMID 33789714, 2021). "Consistently, the analysis of melanoma BM (MBM) revealed that CD271high cells exhibit a lack of expression of MITF and MITF-targets but feature a high enrichment of CD271-target/associated genes (study GSE50493) and genes associated with an NCSC-like phenotype and cell migration." (PMID 32878000, 2020). "However, in this latter study, the authors demonstrated that the SCD1 inhibitor was not effective in the MITF-low/invasive IGR39 and A375M melanoma cell lines." (PMID 33121001, 2020). "NFATc2+ melanomas expressed AXL, N-cadherin and ZEB1, but lacked MITF." (PMID 30710146, 2019). "IGF1 on the other hand induced MITF in NBMEL and nevomelanocytes but not in melanoma cells." (PMID 30675361, 2019).
melanoma (continued). "Despite the enrichment of BRN2 expression in melanoma cells, and the established link of BRN2 to the regulation of MITF expression, the correlation of BRN2 and MITF mRNA levels was not significant in all data sets." (PMID 30277012, 2019). "In comparing IL32 expressing and non-expressing melanoma cell lines, we observed that IL32 expression in melanoma cell lines correlates with a high AXL/low MITF ratio, a genetic signature which has been reported to be associated with a treatment-resistant, dedifferentiation “invasive” phenotype." (PMID 30953519, 2019). "However, MET expression is not controlled exclusively by MITF, as no tight correlations were observed between MITF level and MET expression in other melanoma cell lines." (PMID 30513872, 2018). "On a stiff matrix when YAP is nuclear and co-localizes with PAX3, YAP depletion resulted in a significant decrease in MITF expression, but there was no contribution of YAP to MITF expression in melanoma cells grown on a 0.2 kPa soft matrix when the majority of YAP is cytoplasmic." (PMID 29545604, 2018). "Moreover, MiTF-depleted cells presented a cellular and chromosomal hypersensitivity to ICL-inducing agents similar to that reported in FANCA- or FANCD2-depleted melanoma cells (e and data not shown)." (PMID 27827420, 2016). "MITF regulation by SOX5 has been shown only in murine cells, but not yet in human melanoma cells." (PMID 26927636, 2016). "This study confirmed the negative correlation between MITF and AXL in melanoma cells." (PMID 27102439, 2016). "Moreover, the reduction of MITF expression has been associated to cytoskeletal reorganization and to the phenotype switching, a process similar to epithelial-mesenchymal transition (EMT)-like phenotype (because of their neuroectodermal origin, melanoma cells may not undergo classic EMT)." (PMID 27175588, 2016). "However, MAPKi combination treatment induced cell death and reduced cell numbers in a synergistic manner in BRAF mutant melanoma cell lines, but not in the BRAF mutant/MITF-negative colon cancer cell line RKO." (PMID 26977879, 2016). "Why some melanoma cells appear to express MLANA, but not TYR or MITF, is also not clear, but this hypothesis leads to the prediction that TYR and MITF levels will increase to control levels with time after removal of the melanomas." (PMID 22829910, 2012). "While our study did not specifically analyze ulcerated melanoma subsets, the variations in TIL categories and their correlation with MITF expression suggest a complex interplay that may warrant further stratification based on tumor subtype and clinical features." (PMID 39976551, 2025). "Finally, the MITF-negative undifferentiated cells are prone to lose the expression of SOX10, hence acquiring a preneural crest phenotype upregulating SOX9, as demonstrated in MITF-methylated melanoma cells knocked out for SOX10." (PMID 36551603, 2022). "In order to verify that the link between MITF and the ECM and focal adhesion genes is not restricted to a particular cell line, we performed knockdown and overexpression studies in independent human melanoma cell lines and characterized gene expression data in the Cancer Genome Atlas." (PMID 33438577, 2021). "In the absence of MITF, melanoma cells may become MRD cells by reshaping their ECM, enhancing their attachment to the surface, thus forming quiescent cells which wait for an opportunity to change their phenotype and re-emerge as proliferative melanoma cells." (PMID 33438577, 2021). "However, the inhibitors of PI3K/AKT and ERK, LY294002 and PD98059, could not affect the increased expression of MITF and TYR by 5-HT treatment in B16F10 melanoma cells." (PMID 32961761, 2020). "However, malignant melanoma could be excluded because tumor cells of XP11 TRC were negative for S100 protein and MiTF." (PMID 30103811, 2018).
melanoma (continued). "Interestingly, similar upstream regulators and pathways were significantly altered in melanoma cell lines following BRN2 knockdown, although not MITF and generally with an opposite effect (indicated by the activation z-score) to the changes found with MITF depletion." (PMID 28883623, 2017). "The lack of response in melanoma patients can be explained by several mechanisms of resistance such as melanosomal sequestration of drugs, the upregulation of both DHFR and the pro-survival transcription factor MITF in response to MTX, or the E2F and Chk1 mediated effects, as recently described." (PMID 24941944, 2014). "One prediction is that independent and opposing roles for MITF and PAX3 in melanoma would be expected, and we present empirical evidence supporting this: in melanoma tissues PAX3 expression occurs independently of MITF, and PAX3 does not play a key role in melanoma cell proliferation." (PMID 24062982, 2013).
metastatic melanoma (54 papers, 2008 to 2025). A melanoma that has spread from its primary site to another anatomic site. "In this study we describe that loss of MITF is associated with a distinct transcriptional program, MITF promoter hypermethylation, and poor patient survival in metastatic melanoma." (PMID 36040798, 2022). "MITF gene amplification has been observed in 20-30 % of metastatic melanoma and is associated with decreased overall survival." (PMID 34289891, 2021). "MITF mutations found in metastatic melanoma samples were able to bind DNA and activate expression of melanocyte-specific promoters; some showed increased potential to form colonies." (PMID 34289891, 2021). "Mutations in MITF are associated with Tietz albinism-deafness syndrome and Waardenburg syndrome type 2A, and amplification of MITF is found in 15–20% of human metastatic melanomas and has been linked to poor survival." (PMID 34356645, 2021). "Here, we report that the FANC pathway is highly expressed in metastatic melanoma harboring the oncogenic microphthalmia-associated transcription factor (MiTF)." (PMID 27827420, 2016). "MITF amplification was found in 15-20% of metastatic melanoma, and is associated with decreased 5-year survival." (PMID 20163701, 2010). "Interestingly, in metastatic melanoma, MITF amplification was associated with a decrease in patient survival, similar to our data for miR-211-5p." (PMID 39409187, 2024). "The association between miR-211-5p and MITF may explain the poorer survival of patients with metastatic melanoma when both are strongly expressed." (PMID 39409187, 2024). "In metastatic melanoma, MITF amplification was associated with a survival decrease of 5 years." (PMID 33371469, 2020). "Since metastatic melanoma is a heterogeneous disease, we stratified metastatic melanoma samples into MITFhigh/AXLlow and MITFlow/AXLhigh groups based on their relative MITF and AXL levels." (PMID 37849907, 2021). "In this study, we have explored the role of PTEN in prognosis, therapy response, and immune escape in the context of MITF expression using immunostaining and genomic data from a large cohort of metastatic melanoma." (PMID 32245160, 2020). "In recent reports, 10–15% and 15–20% of human MCMs show MITF gene amplification in primary and metastatic melanomas, respectively, correlated with a decrease in 5-year patient survival." (PMID 29492214, 2018). "In metastatic melanoma, the levels of MITF activity have been proposed to control the cellular phenotype: high levels promote melanocyte proliferation and differentiation, while lower levels confer an invasive state." (PMID 28249010, 2017). "In metastatic melanoma samples, MITF transcript has been determined as a target of miR-182-mediated degradation." (PMID 25433395, 2015). "The lower expression of MITF and related transcriptional networks correlated with increased invasive potential in a panel of cell lines developed from New Zealand patients with metastatic melanoma." (PMID 24733089, 2014). "Expression of the Snail1 and microphthalmia-associated transcription factor (MITF), which is a melanocyte marker, is also increased in metastatic melanoma." (PMID 23785295, 2013). "MITF amplification, single based MITF substitution and even mutation of its regulator SOX10 have all been proven lately to be causative for altered MITF function in both primary and metastatic melanoma underscoring the involvement of MITF in melanomagenesis." (PMID 22007305, 2011). "Further tumor immunohistochemistry revealed extensive neuroendocrine differentiation with CD56, synaptophysin, and INSM1, as well as strong immunoreactivity for melanocyte markers including SOX10, S100, PRAME, and MITF, consistent with metastatic melanoma with neuroendocrine differentiation." (PMID 34926265, 2021). "We speculate that in metastatic melanoma the anti-proliferative effect of very low SOX5 and thus high MITF levels might lead to a diminished susceptibility to chemotherapy and thus to a worse prognosis." (PMID 26927636, 2016).
metastatic melanoma (continued). "Secondary and correlative objectives were to assess whether LBH589 effectively downregulates MITF in biopsy specimens of treated metastatic melanoma." (PMID 27748045, 2016). "This may prove impossible, since metastatic melanomas are heterogeneous tumors with both a highly proliferative population, characterized by high MITF, and a highly invasive population, characterized by low MITF." (PMID 22927992, 2012). "This study will also determine whether LBH589 effectively down regulates MITF in biopsy specimens of treated metastatic melanoma patients." (PMID 21479172, 2011). "By correlating the differential expression of these MITF-M isoforms in primary and metastatic melanoma tissues with progression free survival and overall survival in future studies, we may be able to validate the utility of MITF-Mdel as a biomarker." (PMID 20163701, 2010). "MITF, which was identified in the Met library, showed down-regulation in all skin samples, an increased expression in most nevi and overexpression in 11 out of 25 samples of primary and metastatic melanomas (bottom)." (PMID 18211678, 2008). "However, it has also been found that 15% of metastatic melanomas carry MITF gene amplification." (PMID 35580987, 2022). "In addition, amplification of the MITF locus was observed in human metastatic melanomas." (PMID 22046555, 2011). "The possibility of primary or metastatic melanoma should be considered in differential as it is notorious for its atypical presentation and markers such as Melan A, HMB45, MITF, S100 are helpful in clinching the diagnosis." (PMID 38438897, 2024). "Our study reaffirms and provides an explanation to the coexpression of GHR, MITF, and PGC1A in primary and metastatic melanoma patients." (PMID 31547367, 2019). "Previous reports have also found GHR and MITF as two of the top-20 upregulated genes in the PGC1A-high cohort of GSE7553 dataset of primary and metastatic melanoma patient gene expression." (PMID 31547367, 2019). "Histopathology from T10 vertebral body was suggestive of metastatic melanoma and immunohistochemistry showed strongly positive SOX10, MITF, HMB45, and S100 confirmed metastatic melanoma." (PMID 26989537, 2016). "Also, amplifications in loci 1p12 (NOTCH2), 3p13 (MITF), 13q13.3 (FGF3/4, CTTN) and 22q13 (MLK1) were found in both cytolytic subtypes of metastatic melanoma." (PMID 33779796, 2021). "In contrast to the correlative association between MITF and c-MYC in single-cell RNA-seq data sets on metastatic melanoma, preliminary data indicate that expression of c-MYC appears to be decoupled from MITF at the protein level in bulk MITF-low tumor cells and TERT-immortalized melanocytes." (PMID 30651597, 2019). "Moreover, patient sample analysis confirmed the correlation of SR-BI with MITF and MET in metastatic melanoma lesions." (PMID 30823658, 2019). "Indeed, SCD5 overexpression in metastatic melanoma was sufficient to reduce PRAME, in turn activating MITF and SOX9, which were further increased by ATRA." (PMID 29484133, 2018). "Finally, the analysis of an online database of metastatic melanoma patient-derived tissues (GEO accession number: GDS3966) confirmed similar inversed tendency between SOX10 and ID3 expression on one hand and between MITF and ID3 expression on the other hand (46 samples and 48 samples respectively)." (PMID 29299138, 2017).